TLR4 (toll like receptor 4)
Diseases named in the same sentence as TLR4 in open-access papers (continued):
Sharing a sentence is not in itself a finding about the gene and the disease.
tumor (continued). "When analyzing the relationship between TLR4 expression and clinicopathological features, we found that the expression of TLR4 was not correlated with histologic grade, tumor size, mitotic count, tumor stage and tumor recurrence, but it was significantly correlated with histologic type." (PMID 22985132, 2012). "Not all tumor cells are positive for TLR-4, and this could depend on the tissue from which the tumor cells originated." (PMID 22938142, 2012). "Activation of autophagy after tumor inoculation by using rapamycin, with or without the TLR4/9 agonist complex, could suppress metastasis." (PMID 21931823, 2011). "Although the precise mechanism is required further investigation, tumor cell-induced STAT3 activation may largely be responsible for the suppression of IFNγ/STAT1 signaling and Th1 responses in mice treated with the TLR4/9 agonist complex after tumor cell inoculation." (PMID 21931823, 2011). "However, therapeutic application of the TLR4/TLR9 agonist complex neither induced tumor apoptosis (0.15±0.04) nor attenuated tumor cell proliferation (33.1±11)." (PMID 21931823, 2011). "However, not all tumor cells are positive for TLR-4 and it seems to depend on the tissue from which tumor cells originated." (PMID 17156435, 2006). "Similarly, the Toll‐like receptor 4 (TLR4) signaling pathway contributes to CRC by promoting macrophage activation and infiltration into the colonic mucosa, as well as increasing proinflammatory cytokine expression, fostering an inflammatory microenvironment conducive to tumor development." (PMID 40119640, 2025). "In addition, targeting TLR4 signaling with a TLR4 inhibitor (TAK‐242) reduced the number of infiltrating macrophages and decreased the levels of Inflammatory cytokines in the colon, leading to long‐term effects on tumor growth, which can be beneficial for CRC patients." (PMID 38685971, 2024). "Furthermore, TLR4 KO TAMs were not able to induce the activation of NF-κB in tumor cells." (PMID 38397187, 2024). "Moreover, LPS-induced activation of TLR4 promotes inflammation by stimulating the production and release of pro-inflammatory cytokines (such as TNF-α, IL-1β, and IL-6), thereby indirectly contributing to neoplasia through maintaining proinflammatory microenvironment." (PMID 39328278, 2024). "Tumor cell proliferation in TLR2−/− mice was not promoted because they lacked M2 macrophages while TLR4−/− mice displayed a reduced tumor cell proliferation in response to PepO treatment owing to PepO could prevent TLR4 deficient macrophages from tumor-promoting M2 phenotype." (PMID 37925462, 2023). "It is also important to acknowledge that we relied solely on TLR4 tumor-expression data; whereas evidence from pre-clinical work suggests expression of TLR4 in host tissues (typically non-cancerous) may be critical in setting immune tone of host and thus response." (PMID 35841426, 2023). "Actually, we have investigated published articles on them, but disappointingly, except for TLR4, other four genes are either tumor promoters rather than tumor suppressors both in vivo and in vitro contradicting our present analysis results, or exert different functions in different tumor types." (PMID 37553698, 2023). "Likewise, PepO-primed TLR4−/− M2 BMDM effectively inhibited tumor cell proliferation and TLR2−/− TAM could not promote tumor cell proliferation and reverse EMT due to the lack of M2 macrophages." (PMID 37925462, 2023). "Therefore, IL-10 can regulate the TLR4/NF-κB pathway in dermal fibroblasts through the IL-10 receptor (IL-10R)/STAT3 axis to reduce both ECM protein deposition and fibroblast transformation to myofibroblasts, thereby inhibiting the formation of skin scar induced by lipopolysaccharide." (PMID 36873898, 2023).
tumor (continued). "TLR3, TLR4 and TLR7 are upregulated in certain types of tumour cells, and their expression patterns are associated with tumour progression, suggesting that the innate immunity‐related factors may function as tumour promotors rather than suppressor." (PMID 35050535, 2022). "To further confirm the tumor-inhibition effect of TMED2 and whether it was mediated through the TLR4/NF-κB signaling pathway, we used an activator of TLR4 (sparstolonin B) to boost TLR4 expression and observed the changes in the downstream inflammatory factors using western blotting." (PMID 35135563, 2022). "It is quite remarkable that, despite a well-documented link between TLR4 and cancer, and reasonably convincing evidence that opioids are active at TLR4, the possibility that TLR4 may mediate the effects of opioids on tumour growth and metastasis has not, to date, been explored." (PMID 34771442, 2021). "To examine whether DAMPs are essential for the anti-tumor immune response of Arf1 ablation, we first interfered with the action of ATP and HMGB1 in Lgr5/Arf1/Apc intestinal CSC mice by administering ARL61756 (ARL), oxATP, suramin, and the Toll-like receptor 4 (TLR4) inhibitor." (PMID 31924786, 2020). "Furthermore, evidence suggests that knocking down TLR4 expression by siRNA significantly suppresses the constitutive phosphorylation of Akt and PI3K, and this knockdown may contribute to the inhibition of tumor growth." (PMID 32367494, 2020). "Increased membrane expression of granulocyte TLR4 could impact specific signaling pathways, like NF-kappa B and STAT3, and could mediate molecular mechanisms to promote NADPH oxidase activation and, consequently, ROS production and growth suppression/decay of tumor cells." (PMID 30934946, 2019). "Similarly rhCNB reduced tumor weight in the wild‐type mice but not in their TLR4−/− littermates." (PMID 31218844, 2019). "Furthermore, RPS3 was released from not only B16F1 and B16F10 tumor cells but also normal cells like BMDCs when they were treated with doxorubicin and the released RPS3 could bind to TLR4." (PMID 30819254, 2019). "Moreover, to better understand TLR-4 role on tumor growth, we demonstrated in in vivo study that the absence of TLR-4 strongly inhibited the growth of U-87 tumor xenografts, suggesting that the genetical absence of TLR-4 lead to a greater resistance to the tumor onset and development." (PMID 30680070, 2018). "However, TNFα and IL-6 levels did not increase in TLR4−/− tumor-bearing mice." (PMID 28536426, 2017). "However, TLR4−/− mice were spared from muscle wasting, without altered tumor growth." (PMID 28536426, 2017). "Mechanically, CTC-derived ligands for TLR2 and TLR4 (TLR2/4) induced the systemic inflammation, thus increasing the production of proinflammatory cytokines such as G-CSF and IL-6 that could induce the conversion of neutrophil function from tumor-suppressing to tumor-promoting." (PMID 28415700, 2017). "Thus, research into immunotherapy targeting TLR4/MD-2 complex-mediated MyD88/NF-κB and Akt pathways of EOC cells will probably become focused on an approach to combination immunotherapy that simultaneously intensify anti-tumor immune responses while reversing tumor immune suppression." (PMID 27118139, 2016). "Therefore they state that TLR4 expression may be a prognostic factor of unfavorable evolution in CMM and postulate TLRs and their signaling pathways as potential therapeutic targets to control tumor progression in CMM." (PMID 25973756, 2015). "Thus, the immunosuppressive role of SR-A in cancer might be due to its inhibition of proinflammatory responses by ligation of the toll-like receptor 4 (TLR4) rather than a direct inhibition of tumor immunity." (PMID 24477286, 2014). "It is not yet clear whether TLR4 and MyD88 are involved in tumour initiation." (PMID 20145615, 2010).
tumor (continued). "lactis V9 harmonizes pro- and anti-inflammatory responses through TLR2/TLR4-NF-κB/MAPK signaling, remodels the tumor microenvironment, and enhances αPD-1 efficacy without increasing toxicity." (PMID 42273689, 2026). "While TLR4 and the gut microbiota are not initiating factors in HCC, they play a crucial role in tumor progression by promoting hepatocyte proliferation and inhibiting apoptosis." (PMID 40314129, 2025). "Propionibacterium acnes, frequently enriched in GC tissues, especially in H. pylori–negative cases, promotes M2 macrophage polarization via TLR4/PI3K/Akt signaling, resulting in IL-10 and CCR-2 secretion that fosters immunosuppression and tumor progression." (PMID 41189901, 2025). "Soluble forms of all TLRs were elevated in GC patients, with significant differences based on disease stage but not tumor type, except for serum TLR2, TLR4, and TLR9." (PMID 39451226, 2024). "Parabacteroides diastasonis, a gram-negative bacterium, is capable of reducing tumor incidence in murine models of HFD-induced CRC, and showed the ability to antagonize the TLR-4-MyD88 pathway." (PMID 36838231, 2023). "Both a strong TLR4 expression and the lack of TLR4 expression emerged as markers of aggressive disease, and those patients with metastasized disease had fewer CD45+ lymphocytes around the tumor compared to patients without metastases." (PMID 36649244, 2023). "Early tumor infiltration by activated CD4+ T-cells induced by Lipo-MP-LPS is not due to a direct effect, since lymphocytes do not express TLR4." (PMID 37760603, 2023). "It is interesting to note that OAd-MSC TLR4−/− showed similar tumor homing than noninfected MSCs WT and MSCs TLR4−/−, while homing of OAd-MSC WT to the tumor site was reduced." (PMID 36875156, 2023). "Unlike RAGEs and TLR4, EMMPRIN plays an important role in tumor immunity and metabolism, in which field can be used as a target to design clinical drugs." (PMID 37701037, 2023). "Restoring myeloid cells expressing TLR4 in mice lacking TLR4 reinstated the hepatic inflammation and proliferation triggered by diethylnitrosamine (DEN), underscoring the paracrine mechanism of tumor promotion facilitated by LPS." (PMID 37896221, 2023). "Our results confirm that lack of TLR4 and SARM1 interfere with important tumor-related characteristics such as clonogenic and migration potentials." (PMID 35468924, 2022). "Although there is no discernable difference in TLR4 expression in NPC, as compared with the normal tissues, high levels of TLR4 expression were correlated with increasing tumor grade and nodal metastasis." (PMID 36497484, 2022). "In the present study, we further showed that the activation of TLR4 by M3G did not affect the levels of other common immune checkpoints, including PD-L2, Gal-9, and CD200 on the tumor cells, but just modulated PD-L1 expression." (PMID 33628591, 2021). "determined TLR4 expression on protein level by immunofluorescence and western blot and divided the colon tissue of CAC mice in non-dysplastic and tumor lesions, we analyzed Tlr4 expression on mRNA level in whole colon biopsies of CAC mice." (PMID 34025672, 2021). "The levels of CXCL10 in tumor/non-tumor tissue (p = 0.0148, p = 0.0111) and TLR4 (p = 0.0343) in non-tumor tissue, but not CXCR3, were significantly higher in small-for-size graft than whole graft post-transplantation with tumor recurrence." (PMID 33990548, 2021). "Stimuvax contains monophosphoryl lipid A, which stimulates TLR4; it is useful against the MUC1 tumor antigen but does not alleviate non–small cell lung carcinoma." (PMID 32012718, 2020). "The specific TLR4 inhibitor, CLI‐095, inhibits rapid fetuin‐A uptake, and consequently, most tumor cells, particularly those that do not synthesize fetuin‐A, fail to adhere, spread, or grow in serum‐free medium." (PMID 33073533, 2020).
tumor (continued). "Toll-like receptor 4 (TLR4), a DAMP receptor initially thought to be restricted to immune cells, is present and functional on a variety of non-immune normal cells and tumor cells." (PMID 32426283, 2020). "It has been shown that tumor-exosomes control the expansion of myeloid-derived suppressor cells through TLR2 and not TLR4, which leads to secretion of IL-6 and suppression of CD8+ T cells." (PMID 29867942, 2018). "In consistent, gram-negative bacteria activated TLR4 in NSCLC cells, promoting tumor growth and metastasis." (PMID 29568370, 2018). "Our data also showed that GZMB+-neutrophils have anti-tumor activity when activated by a TLR4 agonist unlike those devoid of GZMB, and their infiltration into tumor probably contributed to the LipA-mediated tumor cell death." (PMID 29983866, 2018). "We found that silencing of TLR2, but not RAGE, TLR4, or CD24, inhibited the migratory ability of the living cancer cells, indicating that HMGB1 regulates tumor cell invasion through TLR2 in vitro." (PMID 29615080, 2018). "Several TLRs had significantly lower mRNA expression in the control versus NSCLC tumor tissue, namely TLR1,2,3,7,9, and 10 while TLR4,5,6 and 8 did not." (PMID 29190881, 2017). "Tumor cells express scavenger receptor genes, but not AGER and TLR4 at significant levels, suggesting that these cells are primarily targeted by S100A8/A9 heterodimers." (PMID 27215396, 2016). "The ethanol-treated and untreated tumor cells (PANC/Mock and PANC/TGF-β) showed sustained expression of HLA-ABC, HLA-A2, MUC1, TLR2, and TLR4, but not HLA-DR, CD80, CD86, and CD83 (data not shown)." (PMID 23717436, 2013). "When this analysis was extended to TGFβ expression at the protein level we found that while TGFβ serum levels in C57BL/6 and RAGE−/− mice increased in tumor-inoculated animals it did not in S100A9−/− and TLR4−/− animals." (PMID 22470535, 2012). "In the EL-4 lymphoma model tumor growth inhibition was observed in S100A9−/− and TLR4−/−, but not in RAGE−/− animals lacking an alternative S100A9 receptor." (PMID 22470535, 2012). "We found that the activation of TLR4 and TLR9 prevented, but did not reverse, metastasis because the potency of this combination was neither sufficient to overcome the tumor cell-educated immune tolerance nor to induce efficacious autophagy in tumor cells." (PMID 21931823, 2011). "We observed a strong correlation between the increased expression of IL-6 and TLR-4 with increasing tissue dysplasia up to malignancy, higher TLR-4 and IL-6 was also found in tumor tissues derived from animals lacking Tir8 as compared to wild-type controls." (PMID 21059221, 2010). "Moreover, Propionibacterium acnes, enriched in H. pylori-negative tumors, can induce M2 macrophage polarization via TLR4/PI3K/Akt signaling, further contributing to immune suppression and tumor progression." (PMID 41189901, 2025). "It has been found that tumor cells in muscle‐invasive bladder cancer patients who do not respond well to radiotherapy can secrete HMGB1 and interact with TLR4 of neutrophils to promote the production of NETs and the survival of tumor stem cells (CSCs), thus forming a feedback loop." (PMID 40979214, 2025). "We believe that unlike LPS that works via TLR4, DAMPs & PAMPs present in tumor cell lysate can induce DC activations through multiple signaling mechanisms (TLR3, TLR4, RAGE, etc.)on DCs, thereby generating dramatic different immunoactivities with β2AR activation vs LPS alone." (PMID 37006295, 2023). "Furthermore, TLR4 expression was found to be correlated with sex and a lower TNM stage but not with age, tumor size, or the differentiation of patients." (PMID 37896221, 2023). "Therefore, in order to confirm the assumption and essentially rule out involvement of TLR4 in ART-induced tumor cell death, TLR4 was silenced in tumor-bearing mice using vivo-morpholino." (PMID 38144525, 2023).
tumor (continued). "Additionally, gram-negative bacteria have been shown to increase metastasis via TLR4 activation in animal models of NSCLC, and NSCLC patients with gram-negative bacterial pulmonary infection or tumor TLR4 overexpression have shorter time to recurrence." (PMID 36303210, 2022). "During tumor progression, no alteration in the expression of Tlr4 was observed in CAC and TAK-242 treated CAC mice compared to healthy control mice, while Abx treated CAC mice displayed a slight but not significant upregulation of colonic Tlr4 expression." (PMID 34025672, 2021). "Interestingly, Tlr4 expression in the colon did not increase at later time points, neither after the last DSS cycle nor during tumor progression." (PMID 34025672, 2021). "In malignant cells lacking TLR4, the same effect could be triggered by HMGB1 indirectly through TLR4-expressing myeloid cells present in the tumour microenvironment (e." (PMID 34234778, 2021). "In an in vitro cell model or in vivo tumor tissues, dipyridamole treatment resulted in a decline in the levels of HMGB1, RAGE, β-catenin, Runx2, YAP1, phosphorylated Smad2/3, and cyclin D1, but not TLR2 and TLR4." (PMID 33669632, 2021). "Additionally, the lack of TLR-4 maintains claudin-5 and DKK-3 proapoptotic properties, resulting in the limitation of tumor expansion." (PMID 32354122, 2020). "The number of tumor specific CD8+IFN-γ+ T cells was greatly increased when mice were vaccinated with RPS3-activated wild type DCs pulsed with E7, but not with RSP3 treated TLR4−/− DCs pulsed with E7." (PMID 30819254, 2019). "For a more efficient outcome, TLR agonists can be used in combination with non-TLR agonists, as demonstrated in a C57BL/6 mice tumor model in which HPV16 E7 vaccine was coadministrated with monophosphoryl lipid A (MPL), a TLR4 agonist, and α-galactosylceramide." (PMID 29854832, 2018). "It is, therefore, reasonable to hypothesize that the balance between a positive signal through TLR4 ligation and a negative signal through Tim-3 ligation might regulate the ICD induced activation of tumor-resident DCs." (PMID 26483791, 2015). "Since RAGE has been shown to be important in tumor growth in other systems, it is not far fetched to suggest that the effect of the S100A9/RAGE interaction might be different than the S100A9/TLR4 interaction in the regulation of tumor growth." (PMID 22470535, 2012). "Toll-like receptor 4 (TLR4), the receptor for LPS, is not only important in the regulation of immune responses to infection, but also is involved in noninfectious inflammatory diseases, such as tumor invasion and survival." (PMID 22938142, 2012). "However, the immunogenicity of tumor cells exposed to ICD-inducer is lost in mice presenting with genetic defects in TLR4 or MYD88, suggesting not all tumor cells will ultimately elicit an antitumor-specific T-cell immunity in the presence of ICD-inducer such as chemotherapy or radiotherapy." (PMID 37142279, 2023). "Indeed, all activators (LPS, IL-4, WGP, and tumor supernatant) upregulated Dectin-1, but not TLR-2 and TLR-4, highlighted an enhancement of Dectin-1 on the non-specific activations of macrophages, perhaps as a preparation for the possible following activations." (PMID 36142859, 2022). "Mechanistically, the cannabinoid receptor CB2 can interact with TLR4 and inhibit the pro-inflammatory signaling of TLR4, while lack of MGLL promotes CB2/TLR4-dependent the M2 phenotype in TAMs, thereby inhibiting the function of tumor-related CD8+ T cells and promoting tumor progression." (PMID 33224886, 2020). "Thus, to understand if the lack of TLR-4 could increase apoptosis in U-87 xenograft tumors, TUNEL staining was performed on tumor sections from tumor sample taken after 28 days." (PMID 30680070, 2018).